UTS2B (urotensin 2B)
Description:
Potent vasoconstrictor.
Synonyms: U-IIB; UIIB; URP; UTS2D; U2B
Tractability: Antibody: its Gene Ontology location is reachable by antibodies, with high confidence; UniProt places it where antibodies can reach, with medium confidence; UniProt predicts a signal peptide or a membrane-spanning region.
Gene: Protein-coding gene on chromosome 3 (191,267,168 to 191,330,572, reverse strand). Ensembl gene ENSG00000188958.
Subcellular location: Secreted
Pathways (Reactome):
Signal Transduction: G alpha (q) signalling events; Peptide ligand-binding receptors
Gene Ontology:
Molecular function: G protein-coupled receptor binding
Biological process: regulation of blood pressure; blood vessel diameter maintenance
Cellular component: extracellular region
Genetic constraint (gnomAD): Loss-of-function variants: 3 observed, 4.58 expected, observed/expected ratio (o/e) 0.65, 90% interval 0.29 to 1.59. That is too few expected variants to judge how well the gene tolerates losing a copy. Missense variants: 43 observed, 38.15 expected, observed/expected ratio (o/e) 1.13, 90% interval 0.88 to 1.45. Synonymous variants: 18 observed, 17.1 expected, observed/expected ratio (o/e) 1.05, 90% interval 0.73 to 1.56.
Homologues: Orthologues: macaque UTS2B (86% identical), chimpanzee UTS2B (82% identical), dog UTS2B (74% identical), pig UTS2B (73% identical), rabbit UTS2B (67% identical), rat Uts2b (52% identical), tropical clawed frog uts2b (50% identical), mouse Uts2b (45% identical).
Diseases named in the same sentence as UTS2B in open-access papers:
UTS2B is named in the same sentence as 5 diseases in open-access papers, as found by Europe PMC text mining. Sharing a sentence is not in itself a finding about the gene and the disease. The quoted sentences say what the papers report.
atherosclerosis (1 paper, 2017). A disease characterized by the build-up of fatty material and calcium deposition in the arterial wall resulting in partial or complete occlusion of the arterial lumen. "The UTS2B gene encodes Urotensin IIB and was shown to play a role in the acceleration of atherosclerosis development." (PMID 28710368, 2017).
myopia (1 paper, 2024). "DIO2 has been previously associated with myopia, as have genes encoding urotensin (e.g., UTS2B)." (PMID 39028695, 2024).
renal failure (1 paper, 2019). "It is worth noting that although protein expression for urotensin system components was high, particularly in the kidneys from the SNx‐L group that were killed immediately before renal failure, attempts to quantify Uts2, Uts2b and Uts2r (UT receptor) mRNA were unsuccessful." (PMID 30575177, 2019).
UTS2B also shares sentences with these, for which no sentence is quoted: glioma (1 paper); prostate carcinoma (1).